IL1B (interleukin 1 beta)
Diseases named in the same sentence as IL1B in open-access papers (continued):
Sharing a sentence is not in itself a finding about the gene and the disease.
psoriasis (continued). "Interaction of S100A7 with RAGE activates p38 MAPK (mitogen-activated protein kinase) and ERK (extracellular signal-regulated kinase) signaling pathways, leading to production of multiple inflammatory mediators involved in psoriasis, including IL-1α, IL-1β, IL-6, IL-8, TNF-α." (PMID 37346040, 2023). "Furthermore, tapinarof exhibits direct binding to the aryl hydrocarbon receptor (AhR), leading to a reduction in the production of inflammatory cytokines, including IL-17A, IL-17F, IL-22, IL-23, and IL-1β, as demonstrated in a psoriasis-like mouse model." (PMID 38288335, 2023). "Interestingly, in the HS samples, there was a predominance of the IL-1β–T17 cell cytokine axis, indeed suggesting that T17 cells are likely to be activated by IL-1β in HS, while psoriasis T17 cells are activated by IL-23 signaling." (PMID 37896210, 2023). "In addition, MCs can capture, store, and release exogenous IL-17A, and can release extracellular traps and degranulate upon stimulation of IL-23 and IL-1β, which are major cytokines involved in psoriasis pathogenesis." (PMID 37681909, 2023). "Furthermore, genetic polymorphisms of TLRs, IL-1β, LY96, and TIRAP have been associated with a response to anti-TNFα or ustekinumab in psoriasis." (PMID 37511413, 2023). "Adoptive transfer with Tomato-expressing BMDMs restored Mincle-expressing macrophage infiltration and inflammatory responses as demonstrated by upregulation of pro-inflammatory cytokines (IL-1β and IL-6), Mincle and iNOS, resulting in the development of severe skin lesion in psoriasis mice." (PMID 37117184, 2023). "In addition to keratinocytes, macrophages, neutrophils, lymphocytes, and mast cells produce high levels of cytokines such as TNF-α, IL-1β, and IL-6 to maintain the positive feedback cycle in psoriasis." (PMID 37585684, 2023). "While the exact cause of psoriasis is not fully elucidated, it is believed that abnormal immune function, especially the excessive secretion of inflammatory factors such as IL-1β and IL-6, contributes substantially to its development." (PMID 37554338, 2023). "In patients of psoriasis, a disease with chronic systemic inflammation, MDSCs produce IL-1β." (PMID 35464987, 2022). "In the current study, coptisine inhibited the LPS-induced secretion of TNF-α and IL-1β in BV2 microglial cells, suggesting that coptisine might attenuate psoriasis-associated neuroinflammation by suppressing microglial activation." (PMID 35209199, 2022). "In addition, the IL-1β levels in the saliva of psoriatic patients positively correlate with psoriasis activity." (PMID 35454992, 2022). "For example, because miR-31 is highly over-expressed in psoriatic skin and could enhance NF-κB signaling pathway and IL-1β production, specific inhibition of miR-31 by its antisense strand could dramatically suppress the progression of psoriasis." (PMID 36618400, 2022). "NSA, or chemically similar compounds, may be of value in the treatment of IL-1β-mediated conditions, such as PAPA and HS, and in diseases associated with NETosis, including vasculitis, SLE, and psoriasis." (PMID 35929827, 2022). "In addition, we found higher NLRP3, ASC, caspase-1 and IL1B mRNA levels in PBMCs from psoriasis patients compared with healthy individuals." (PMID 36293012, 2022). "In the pathogenesis of psoriasis, IL-17 interacts with keratinocytes to promote the production of antimicrobial peptides, proinflammatory cytokines and chemokines (IL-1β, TNF-α, IL-6, IL-17C, CXCL1, CXCL3, CXCL5, CXCL8 [IL-8] and CCL20) and proliferative cytokines (IL-19)." (PMID 35514987, 2022). "In the context of autoimmune disorders, MCs from human skin explants exposed to IL-23 and IL-1β or derived from psoriasis patients have been shown to release ETs decorated with chymase and IL-17, which might contribute to psoriasis." (PMID 35844591, 2022).
psoriasis (continued). "For example, neutrophils and macrophages are the major sources of IL-1β in a murine psoriasis model, while keratinocytes may be the primary source of IL-1β in human psoriasis." (PMID 36013129, 2022). "Thus, IL-1β is now emerging as a critical cytokine in the pathogenesis of IL-17-mediated skin disorders, and in particular, psoriasis." (PMID 35663672, 2022). "Taken together, these findings suggest that IL-1β might be a promising therapeutic target for psoriasis intervention." (PMID 35153790, 2022). "In psoriasis lesions, IL-6 and IL-1β are released from stimulated keratinocytes." (PMID 36620087, 2022). "Consequently, SHP2‐mediated TLR7/NF‐κB activation was augmented, leading to further increases in the expressions of psoriasis‐related inflammatory cytokines, including IL‐23A, TNF‐α, IL‐6, and IL‐1β, thus accelerating psoriasis‐like skin inflammation." (PMID 34936223, 2022). "Consistent with the ameliorated psoriasis‐like phenotype, the mRNA levels of genes related to the IL‐23/IL‐17 axis, such as Il23a, Il17a, and Il22, and the expression of Tnfa, Il6, and Il1b was decreased in the skin." (PMID 34936223, 2022). "Furthermore, a recent study using a mouse psoriasis model indicated the inhibitory role of estrogens in psoriatic dermatitis by suppressing IL-1β production from neutrophils and macrophages." (PMID 36013129, 2022). "Unexpectedly, pro-inflammatory genes, including CXCL1, CCL2, and IL-1β, which may lead to severe inflammation in psoriasis patients, were downregulated by miR-193b-3p mimics in the presence or absence of M5 treatment." (PMID 34667159, 2021). "In addition, IL-1β, IL-23 and IL-17a are also very important cytokines involved in the pathogenesis of psoriasis." (PMID 34220863, 2021). "Despite differences in major IL-1β-producing cells between mouse models and human disease, we speculate that the inhibition of IL-1β production can be a treatment for psoriasis, similar to the inhibition of IL-17 production." (PMID 34421919, 2021). "Furthermore, we detected an upregulation of Il1b, whose proinflammatory role in psoriasis has been described previously." (PMID 34440590, 2021). "IL-1β is reported to play a role early in psoriasis disease development." (PMID 34884681, 2021). "IL-2 and IL-1β, together with theconcentrations of leucine, alanine, glutamine, glutamate, and choline,can be considered promising biomarkers for the early diagnosis andcorrect prognosis of psoriasis patients." (PMID 33164516, 2021). "Luteolin reduced IL-1β, IL-17A, IL-23, and IL-6 which could contribute to the anti-inflammatory effects of this flavonoid and the reduction of psoriasis damage in the mice model." (PMID 34943117, 2021). "The IL-1 pathway resulted hyperactive in HS, and van der Zee and colleagues showed not only that IL-1β levels were significantly elevated both in lesional and perilesional HS skin, but that they were also higher than in psoriasis skin (the prototype inflammatory skin disease)." (PMID 34572354, 2021). "IL-24 is a member of the IL-20 family induced by IL-6, TNF, and IL-1β in psoriasis." (PMID 34054833, 2021). "In addition, TNF-α, IL-6, and IL-1β are important proinflammatory cytokinesthat are related to the pathogenesis of psoriasis." (PMID 34202301, 2021). "IL-17A is important in relieving psoriasis by upregulating cytokines IL-6, IL-1β, and TNF-α." (PMID 34054833, 2021). "Therefore, to appraise the role of apremilast in vivo and on the innate immune system, we assessed the effect of apremilast in a transgenic mouse model of psoriasis and evaluated its effect on the expression of inflammatory cytokines, including IL-1β." (PMID 34884681, 2021). "We transfected si-ATG5 and pc-ATG5 into HaCaT cells and detected the expression of IL-6 and IL-1β to investigate whether the ATG5 gene could be used as a therapeutic target for the management of psoriasis." (PMID 34113484, 2021).
psoriasis (continued). "Similarly, another recent study investigated the effect of low-calorie ketogenic diet in 30 patients with psoriasis by evaluating clinical symptoms, biochemical markers, metabolomic profile and inflammatory markers (IL-2, IL-4, IL-1β, TNF-α, IFN-γ)." (PMID 33499118, 2021). "In addition, IL-1α expression is decreased, whereas IL-1β expression is increased in the lesional skin of psoriasis patients." (PMID 32194991, 2020). "Skin commensal organisms are altered in psoriasis and may contribute to the development of psoriasis by regulating γδ T-cell function via IL-1β." (PMID 32917058, 2020). "Interestingly, IL-1β, which was altered in our mouse model during psoriasis, directly or indirectly influences the expression of various VEGFs and their receptors." (PMID 31357710, 2019). "Hence, cytoplasmic DNA appears to contribute to the pathogenesis of psoriasis via activation of IL-1β in keratinocytes by AIM2-mediated inflammasomes." (PMID 31877866, 2019). "The activity of inflammatory cytokines, including TNF-α, IL-6 and IL-1β, is considered to take responsibility for the development of psoriasis; hence, decreasing their levels might contribute to improvement of the disease." (PMID 31252651, 2019). "Then, growth factors and relevant cytokines (IL-17A, TNF-α, and IL-1β) in psoriasis activate mTOR and promote keratinocyte hyperproliferation and inhibit differentiation, which might be the mechanism underlying the PI3K/Akt pathway and psoriasis." (PMID 31824416, 2019). "Anti-psoriasis mechanism studies have indicated that compound 5c reduced the secretion of IL-1β, IL-6, IL-8 and IL-24 in an IMQ-stimulated model and could also attenuate the activation of IMQ-induced MAPKs, including JNK1/2 and ERK1/2." (PMID 30301277, 2018). "In the complex immunopathology of psoriasis, it is thought that during innate immune activation, plasmacytoid dendritic cells (pDCs) are activated together with IL-1β and TNF-α producing keratinocytes in response to dendritic Toll-like receptor activation by DNA (LL-37)." (PMID 29713318, 2018). "In psoriasis, Compound 5c reduced IL-6, IL-8, IL-1β and IL-24 in imiquimod-stimulated models." (PMID 30301277, 2018). "The authors reported a statistically significant greater expression of TNF-α, TGF-β1, MCP-1, and IL-1β in saliva of patients with psoriasis than in healthy subjects, with a positive correlation between IL-1β, TGF-β1, and MCP-1 expression and oral disease severity." (PMID 29888276, 2018). "Cytokines such as IL-1β, IL-17A, IL-22 and IL-23, which are involved in the pathogenesis of psoriasis, may also contribute to the production of IL-1β." (PMID 28266627, 2017). "In addition, we inhibited CCN1 function in mouse models of psoriasis, and decreased IL-1β production was observed in vivo." (PMID 28266627, 2017). "To confirm these results, we blocked CCN1 function with a monoclonal antibody in imiquimod (IMQ)-induced psoriasis-like mice or with a lentiviral vector expressing short hairpin RNA (shRNA) in IL-23-induced psoriasis-like mice, and we also found impaired IL-1β expression in vivo." (PMID 28266627, 2017). "It has been showed that IL-1α, IL-1β, IL-17A and IL-23 are important to psoriasis progress." (PMID 28060905, 2017). "Current studies link IL-1β production and Th17-mediated effects in autoimmune diseases, including psoriasis, and these observations could contribute to the developing understanding of their pathogenesis and therapeutic interference." (PMID 28422993, 2017). "Thus, our results indicate that CCN1 not only directly activates keratinocytes but is also involved in the amplification cycle for the chronic inflammation of psoriasis by enhancing IL-1β expression." (PMID 28266627, 2017). "Moreover, these immune cells release growth factors, chemokines, and pro-inflammatory cytokines such as tumor necrosis factor (TNF)-α, interleukin (IL)-6, IL-1β and IL-17, which interact as a network in the pathogenesis of psoriasis." (PMID 29295585, 2017).
psoriasis (continued). "Aside from a potential link to HLA, also the presence of the polymorphism +3954 IL-1B was shown to be associated with increased risk of GT; the product of the altered gene, interleukin 1B (IL-1B), is known to play a pivotal role in the pathogenesis of psoriasis as well." (PMID 28905102, 2017). "Curcumin could also demonstrate the inhibitory effect in lmiquimod-induced psoriasis-like inflammation by decreasing the levels of IL-1β and IL-6." (PMID 26007179, 2015). "In contrast to IL-17 and IL-22, which suppressed chemerin expression, OSM and IL-1β significantly increased chemerin production, despite the fact that all four cytokines are potent keratinocyte activators with potential roles in the pathology of psoriasis." (PMID 25659101, 2015). "We also uncovered “psoriasis response elements” (PREs) overrepresented in psoriasis DEG promoter regions, which are present within enhancers near cytokine-encoding genes (e.g., IL17A, IL19 and IL1B)." (PMID 25883770, 2015). "Finally, slanDC, another inflammatory DC subset found in psoriasis, also induce the release of IL-1β, IL-6, TNF, IL-12, and IL-23 in response to LL37/self-RNA complexes." (PMID 26229971, 2015). "Specifically, glutamine consumption enhances the production of many cytokines, and among them, tumor necrosis factor-α (TNF-α), interferon-γ (IFN-γ), interleukin-1β (IL-1β), and interleukin-6 (IL-6), all of which play an important role in psoriasis innate immunity." (PMID 25580230, 2014). "We therefore speculate that, while the role of IL-1β in psoriasis remains unclear, its activity may nonetheless reinforce activation of the cytokine network within psoriasis lesions." (PMID 23915137, 2013). "An in vitro study in peripheral blood mononuclear cells (231 cases and 345 controls) revealed an association between the CC genotype in rs16944 in the IL1β gene with increased production of IL1RA in response to lipopolysaccharide and IL10 and late-onset psoriasis (over 40 years)." (PMID 24069534, 2013). "Also, mice with psoriasis had significant increases in specific pro-inflammatory cytokines (IL-1β, IL-6 and IL-12) and decreases in the anti-inflammatory cytokine (IL-10) after PSD, which were normalized after 48 h of sleep rebound." (PMID 23226485, 2012). "Similarly, the pathogenesis of psoriasis involves key Th1 and Th17 inducing cytokines like TNFα, IL-1β, IL-2, IL-6, IL-10, IL-12p70, IL-23, CCL2, 3, 4, 5, 20, CXCL1, 8, 9 and 10, many of which are induced by cocktail treated DCs." (PMID 20663192, 2010). "Therefore, the factors, including IL-17A, IL-22, IL-1β, NLRC4, MEFV, and CASP5, detected by ocular surface test in our case should be verified for their usefulness as biomarkers for psoriasis-associated conjunctivitis in clinical studies involving a large number of cases." (PMID 40861543, 2025). "Furthermore, inflammatory cytokines relevant to psoriasis pathogenesis, including Il17a, Tnfa, and Il1b, as well as neutrophil‐attracting chemokines, such as Cxcl1 and Csf3, were significantly upregulated at the mRNA level in Fads2‐silenced skin lesions compared to controls." (PMID 40878384, 2025). "In psoriasis, various stress-related triggers—ranging from environmental factors to genetic predispositions—can activate innate immune cells and keratinocytes to produce tumor necrosis factor-α (TNF-α), interferon-γ (IFN-γ), IFN-α, interleukin-6 (IL-6), and interleukin-1β (IL-1β)." (PMID 40731810, 2025). "Therefore, it is hypothesized that the occurrence of neutrophil pyroptosis in psoriasis may activate inflammatory pathways downstream by releasing cytokine IL-1β." (PMID 39717896, 2024). "IL-1β released by pyroptosis may amplify the inflammatory cascade through the IL-1β-IL-1R pathway via direct regulation of dermal IL-17-producing cells and stimulation of keratinocytes, thereby contributing to skin inflammation and psoriasis." (PMID 39717896, 2024).
psoriasis (continued). "When environmental and genetic factors activate plasmacytoid dendritic cells, cytokines such as TNF-α, IL-6, and IL-1β are released, leading to T cell-mediated inflammation, keratinocyte activation, and excessive proliferation, resulting in inflamed skin patches characteristic of psoriasis." (PMID 39170985, 2024). "In addition, pretreatment of HaCaT cells with polar microalgae extracts significantly decreased expression of IL1B, IL23, CXCL1, and IL17A mRNA, which are mediators implicated in the pathogenesis of psoriasis, compared to HaCaT cells treated with only M5 cytokines." (PMID 37438821, 2023). "We firstly found that the IMQ-induced psoriasis-related female mice showed depressive- and anxiety-like behaviors, which were associated with microglial activation, the up-regulation of NLRP3, Caspase-1, IL-18, and IL-1β, and the down-regulation of CRMP2 and α-tubulin." (PMID 36138986, 2022). "employed CRISPR-Cas9 technique to knock out Myd88 gene in epidermal keratinocytes, and indicated that Myd88 knockout could significantly reduce the expression of its downstream IL-1β and IL-36, which are two important factors regulating the inflammatory response of psoriasis." (PMID 36618400, 2022). "In this study, we present another evidence that targeting IL-1β by PUN could ameliorate psoriasis." (PMID 35153790, 2022). "Thus, the anti-psoriatic effects of E2 through the inhibition of IL-1β production by neutrophils and macrophages may be limited in human psoriasis." (PMID 36013129, 2022). "Sleep deprivation in mouse models of psoriasis led to increased levels of pro‐inflammatory cytokines, including IL‐1β, IL‐6 and IL‐12, resulting in enhanced inflammatory immune response and suggesting that circadian disruption could contribute to the pathogenesis of psoriasis." (PMID 35851722, 2022). "Taken together, our findings indicate that PUN can relieve psoriasis by repressing NF-κB-mediated IL-1β transcription and caspase-1-regulated IL-1β secretion, which provide evidence that PUN might represent a novel and promising candidate for the treatment of psoriasis." (PMID 35153790, 2022). "Furthermore, both in psoriasis and AD IL1B gene expression levels are increased." (PMID 33683743, 2021). "Thirty psoriasis patients were subjectedto a ketogenic nutritional regimen and monitored by evaluating (i)the clinical symptoms, (ii) the blood biochemical parameters, includingIL-2, IL-1β, TNF-α, IFN-γ, and IL-4, and (iii) themetabolomic profile, as derived from 1H NMR analysis." (PMID 33164516, 2021). "Because IL-1β has a critical role in the differentiation and activation of IL-17-producing T cells, IL-1β may be directly or indirectly involved in the exacerbation of psoriasis by promoting Th17 cell polarization." (PMID 34421919, 2021). "In summary, this work may form the basis for future investigations studying the impact of abrogation of IL‐1β signalling on PPARγ and its effects on normalization of barrier homeostasis in common inflammatory skin disorders such as atopic dermatitis and psoriasis." (PMID 33683743, 2021). "Additionally, several cytokines, such as tumor necrosis factor (TNF)-α, interleukin (IL)-1β, IL-12, IL-17A, IL-22, and IL-23, upregulate the production of reactive oxygen species and the hyperproliferative keratinocyte state seen in psoriasis, and are shown to play a role in some malignancies." (PMID 34685480, 2021). "Th17 cells, as well as Th1 cells and keratinocytes, secrete TNF-α, IFN-γ, IL-1β, IL-6, IL-12, IL-17A, IL-22, IL-23 participating in pathophysiologic processes of psoriasis and current biological therapies as T cell-directed agents have demonstrated excellent efficacy in psoriasis." (PMID 33685393, 2021). "However, a study from 2015 showed higher salivary levels of pro‐inflammatory cytokines, including tumor necrosis factor‐α, IL‐1β, transforming growth factor‐1β, and monocyte chemoattractant protein‐1 in patients with psoriasis as compared to orally healthy controls." (PMID 31916654, 2020).